PALB2 (partner and localizer of BRCA2)
Diseases named in the same sentence as PALB2 in open-access papers (continued):
Sharing a sentence is not in itself a finding about the gene and the disease.
breast cancer (continued). "BARD1, PALB2, and RAD51B variants have been identified in breast cancer families, whereas truncating RAD51C and RAD51D variants are mainly found in families with ovarian cancer or breast and ovarian cancer." (PMID 30689231, 2019). "We conclude that the breast cancer risk association of these two FANCC variants, if any, is much smaller than for BRCA1, BRCA2 or PALB2 mutations." (PMID 31467304, 2019). "Germline pathogenic variants in DNA repair genes BRCA1, BRCA2, PALB2, ATM, and CHEK2 are associated with breast cancer risk." (PMID 31700994, 2019). "In contrast, we observed a clear association between the PALB2/FANCN variant p.R414X and breast cancer risk." (PMID 31467304, 2019). "The first cases of a PALB2, an APC and a NTHL1 pathogenic variants in patients with both breast cancer and NET were presented." (PMID 31592449, 2019). "Finally, we sought to define whether PALB2-associated breast cancers with bi-allelic PALB2 inactivation would differ from breast cancers arising in BRCA1 and BRCA2 pathogenic germline mutation carriers with bi-allelic inactivation of BRCA1 and BRCA2, respectively." (PMID 31428676, 2019). "Among high-risk genes for breast cancer BRCA2 (1.9% (23/1197)) and PALB2 (1.7% (20/1197)) had the highest VUS rates." (PMID 31159747, 2019). "We demonstrated for the first time that higher expression of PALB2 was correlated with poor prognosis for advanced breast cancer patients." (PMID 29321957, 2018). "Two frameshift deletions resulting in predicted premature termination codons were identified: PALB2:c.509_510del; p.R170Ifs in three women affected with breast cancer and PALB2:c.172_175del;p.Q60Rfs in one woman affected with ovarian cancer." (PMID 29052111, 2018). "In the current study, we investigated the expression of PALB2 in human breast cancer tissues and its correlation with the prognosis for breast cancer patients." (PMID 29321957, 2018). "Targeted-sequencing identified two frameshift deletions: PALB2:c.509_510del; p.R170Ifs in three women affected with breast cancer and PALB2:c.172_175del;p.Q60Rfs in one woman affected with ovarian cancer." (PMID 29052111, 2018). "A frameshift deletion in PALB2 was found in one member of a family with a history of gastric and breast cancer." (PMID 29706558, 2018).
breast cancer (continued). "A more intermediate risk of developing breast cancer is conferred by germline mutations in the genes CHEK2, ATM, PALB2, and NBS1, which are, in the general population, more prevalent than mutations in the high risk breast cancer genes." (PMID 30116257, 2018). "Overrepresentation of triple negative status in PALB2-related breast cancers was suggested in studies performed in European cohorts." (PMID 30257646, 2018). "In immunohistochemical analysis, we found increased expression of PALB2 in breast cancer tissues compared with the adjacent normal ductal epithelium (P < 0.001)." (PMID 29321957, 2018). "Additional germline variants in several other genes, including PALB2 (partner and localizer of BRCA2) (MIM#610355) have also been implicated in increased predisposition to breast cancer." (PMID 30410870, 2018). "We examined the PALB2 expression level in several human breast cancer cell lines, namely MCF‐7, T47D, MDA‐MB‐468 and MDA‐MB‐231, by western blot." (PMID 29321957, 2018). "PALB2 high expression was also found to predict poor overall survival in advanced breast cancer patients." (PMID 29321957, 2018). "In several populations, mutations in PALB2 and FANCM confer the moderate to high risk for breast cancer." (PMID 30007403, 2018). "Knockdown of PALB2 inhibits the migration and invasion ability of the breast cancer cells through increased E‐cadherin expression level and decreased N‐cadherin expression level." (PMID 29321957, 2018). "Higher expression of PALB2 was also found in the highly metastatic breast cancer cell line MDA‐MB‐231 compared with low invasion capacity cell lines such as MCF‐7, T47D and MDA‐MB‐468." (PMID 29321957, 2018). "No PALB2 or very low PALB2 expression level (all IHC score < 0.5) was observed in the adjacent normal tissues, while a significantly higher PALB2 score was detected in breast carcinoma samples (mean IHC score = 1.22, P < 0.001)." (PMID 29321957, 2018). "Other potential sources of DNA repair deficiency in breast cancer, also involving DSB repair processes, include germline mutations in DNA repair genes PALB2, FANCM, ATM, CHEK2 (and possibly also RAD51C) characterized as loss-of-function variants." (PMID 28679371, 2017). "In LCLs from heterozygous carriers of a FA subtype N (FancN/PALB2)-mutation, which increases breast cancer risk six-fold, we previously found a relative increase of total NHEJ, but to a significantly lesser extent than SSA." (PMID 29228718, 2017). "Further association studies, in families and in the general population, are needed to confirm the association of genes such as ATM and PALB2 with MBC and to calculate more precise breast cancer risks for males with pathogenic variants in these genes." (PMID 28008555, 2017). "PALB2 predicted promoter region was mostly observed hypermethylated in tumors from an Australian cohort of hereditary breast cancer cases." (PMID 28858227, 2017).
breast cancer (continued). "The mutated tumor suppressor gene, PALB2 largely affects BRCA2, which increase the risk of BRCA1/2 based breast cancer." (PMID 28477017, 2017). "Here we have genotyped the CHEK2 mutations I157T and c.1100delC, the FANCM mutation p.Q1701X, the PALB2 mutation c.1592delT, the RAD51C mutations c.837+1G>A and c.93delG, and the RAD51D mutation c.576+1G>A in 68 male breast cancer patients." (PMID 28874143, 2017). "Nine genes in this module – Akt1, Brca2, Ccnd1, Dnmt1, Mki67, Palb2, Rrm1, Timeless, and Top2a – are known human breast cancer genes according to the MalaCards database; four of them are hub genes." (PMID 28212608, 2017). "Known genetic factors contributing to a higher lifetime risk of breast cancer comprise rare variants in BRCA1, BRCA2, PALB2, ATM and CHEK2." (PMID 28199975, 2017). "Mutations in high-risk breast cancer genes or genes associated with syndromic diagnoses (CDH1, PALB2, PTEN, STK11, and TP536, 20, 21) were identified in 1.4% of the FBC cohort." (PMID 28649662, 2017). "Within breast cancer patients, approximately 10% are heterozygous mutation carriers of the BRCA1/BRCA2/PALB2 gene, and their cancer resulted from the loss of heterozygosity." (PMID 29023372, 2017). "Most pathogenic mutations were in genes with an established breast cancer risk (ATM, BRCA1, CHEK2, and PALB2)." (PMID 28281021, 2017). "Here, we describe the generation of a novel mouse model that has a single amino acid alteration in the BRCA2 protein that affects its interaction with another hereditary breast cancer protein, PALB2." (PMID 27490902, 2016). "Pathogenic variants were identified in 11.8% (6/51) of male patients with breast cancer and were found in BRCA1, BRCA2, CHEK2, and PALB2; one man was positive for both a BRCA1 and CHEK2 variant." (PMID 26681312, 2016). "Mutations in PALB2 are associated with increased risk of breast cancer, similar to that of BRCA2, making it an important hereditary breast cancer susceptibility gene." (PMID 27490902, 2016). "The PALB2 p.G998E variant in this patient was reported at a similar frequency of ~ 10% in a population of BRCA1- and BRCA2-negative male breast cancer patients in Northern Italy as was observed in healthy individuals." (PMID 26485759, 2015). "Other relevant genes also contribute to inherited breast cancer, among these genes is PALB2 (Partner and Localizer of BRCA2) gene." (PMID 26489409, 2015). "The results show that mutations in PALB2 are rare, but along with BRCA1 and BRCA2 are key breast cancer susceptibility genes in the Xinjiang region of China." (PMID 26489409, 2015). "This study aimed to evaluate the contribution of germline BRCA1, BRCA2 and PALB2 mutations and the CHEK2 c.1100delC allele to breast cancer in a high-risk South African cohort." (PMID 26577449, 2015). "Since these initial reports, there has been a wide array of population-based studies describing the prevalence of PALB2 in breast cancer cases with incidence ranging from 0.5% to 2.6%." (PMID 24949998, 2014). "In our previous studies, we screened a series of breast cancer susceptibility genes within the HR repair pathway, including BRCA1/2, PALB2, RAD50, and NBS1, in Chinese women." (PMID 25360583, 2014).
breast cancer (continued). "- PALB2: Subsequently, the “partner and localiser of BRCA2”, PALB2, has been identified as another breast cancer susceptibility gene." (PMID 24025454, 2013). "Biallelic mutations of some of these hereditary breast cancer susceptibility genes, namely BRCA2/FANCD1, BRIP1/FANCJ, PALB2/FANCN and RAD51C/FANCO, have been identified in patients with Fanconi anemia (FA, [MIM 227650])." (PMID 23840564, 2013). "For example, PALB2 c.1592delT was identified in 18/1,918 (0.9%) Finnish breast cancer cases, unselected for family history, compared to 6/2,501 (0.2%) in controls (OR 3.94; 95% CI 1.5 to 12.1)." (PMID 23448497, 2013). "Our results are consistent with previously established frequency of PALB2 c.2323C>T [p.Q775X] carriers in breast cancer families of French Canadian descent." (PMID 23302520, 2013). "There were 21 cases that also had a prior personal history of breast cancer and the PALB2 p.Q775X carrier was in the group of 10 invasive serous ovarian carcinoma cases with this history." (PMID 23302520, 2013). "In summary, six PALB2 p.Q775X breast cancer carriers which include five occurring in apparently unrelated cancer families have thus far been identified in screening breast cancer cases or breast cancer families." (PMID 23302520, 2013). "PALB2 methylation has been reported in familial and sporadic breast cancer cases as well as in sporadic ovarian cancer samples." (PMID 23587053, 2013). "The average age for the onset of breast cancer in PALB2 c.1592delT carriers is 53.1 years, which is somewhat higher than in Finnish BRCA1/BRCA2 mutation carriers (45.2/47.4 years), but considerably lower than in sporadic patients (58.0 years)." (PMID 23941127, 2013). "The PALB2 carrier had bilateral invasive ductal carcinomas of the breast at ages 39 and 42 and is part of the breast cancer family F1469." (PMID 23302520, 2013). "Chen et al65 used the GenomeLab SNPstream 12-plex Genotyping System to study SNPs of PALB2 in a cohort of 1049 breast cancer cases and 1073 controls in a Chinese population." (PMID 23318652, 2013). "However, as the PALB2 c.1592delT founder mutation, with a frequency of roughly 1% also in Finnish breast cancer cases unselected for their family history of disease, increases the risk of breast cancer in a way comparable to that of BRCA2, targeted clinical testing for c.1592delT seems appropriate." (PMID 23941127, 2013). "Our findings here support this notion, as the PALB2 p.Q775X carrier identified had a bilateral case of breast cancer diagnosed before age 45 years and a strong family history of breast cancer." (PMID 23302520, 2013). "The young ages of breast cancer diagnoses and number of breast cancer cases per family in PALB2 p.Q775X carrier families suggest that carriers of this mutation are at high risk for breast cancer, as has been posited with some PALB2 mutation carrier families." (PMID 23302520, 2013). "Among them, PALB2 (partner and localizer of BRCA2) has emerged as a breast cancer susceptibility gene in several populations world-wide." (PMID 23941127, 2013). "It is interesting that the PALB2 p.Q775X carrier found among the ovarian cancer cases examined in this study had a prior history of breast cancer." (PMID 23302520, 2013). "We identified a PALB2 p.Q775X carrier in a breast cancer family, who had invasive ductal breast carcinomas at 39 and 42 years of age." (PMID 23302520, 2013). "So far, while BRCA2, BRIP1, PALB2, and RAD51C are associated with high or moderate breast cancer risk, the impact of SLX4 on breast cancer remains to be measured." (PMID 22383991, 2012). "Mutations of CHEK2, PALB2, and BRIP1 have a 2.34, 2.3, and 2.0 fold increase risk for breast cancer compared to the normal population, respectively." (PMID 22606018, 2012).
breast cancer (continued). "Some of the genes causing the Fanconi anemia (FA) syndrome, such as BRCA2, BRIP1, PALB2, and RAD51C, are associated with high or moderate risk of developing breast cancer." (PMID 22383991, 2012). "PALB2, like BRCA2, is a breast cancer suppressor and is also associated with Fanconi anemia, a developmental and tumor predisposition syndrome." (PMID 22194698, 2011). "W31C mutation, which is annotated in the Breast Cancer Information Core (BIC) database, impairs the interaction of full-length BRCA2 with PALB2 and impairs HR function." (PMID 22194698, 2011). "We then used a TaqMan assay to screen women diagnosed with breast cancer between the ages of 40 and 59 years and control probands participating in the ABCFR for the PALB2 c.3113G > A mutation." (PMID 21182766, 2010). "To date, all PALB2 gene alterations detected in families with breast cancer or FA disease were frameshift or nonsense changes, leading to the expression of a truncated protein." (PMID 20122277, 2010). "Further screening for PALB2 c.3113G > A (W1038X) was conducted for 779 families with multiple cases of breast cancer ascertained through family cancer clinics in Australia and New Zealand and 764 population-based controls." (PMID 21182766, 2010). "Breast cancer risk is also influenced by rarer variants that confer moderate breast cancer risks such as ATM, CHEK2, BRIP1 and PALB2." (PMID 20146796, 2010). "In the past year, Dr. Marc Tischkowitz and colleagues have focused on determining the contribution of a new breast cancer gene, PALB2, to the incidence of breast cancer in Quebec." (PMID 18596893, 2008). "Mutations in ATM, BRIP1, PALB2, CHEK2 and possibly NBS1, RAD50 are also associated with a moderately increased risk for breast cancer, and many low penetrance genes have recently been identified." (PMID 18706089, 2008). "Several mutations in the PALB2 gene (partner and localizer of BRCA2) have been associated with an increased risk of breast cancer, including a founder mutation, 1592delT, reported in Finnish breast cancer families." (PMID 18637200, 2008). "Previously, we and others showed that most breast tumors arising in PALB2 mutation carriers are ER+, PR+, and HER2-, like both BRCA2-related and sporadic breast cancer." (PMID 18053174, 2007). "We screened all coding exons of PALB2 in a sample of 50 French-Canadian women diagnosed with either early-onset breast cancer or familial breast cancer at a single Montreal hospital." (PMID 18053174, 2007). "Here, two of the three families were moderately suggestive of hereditary breast cancer and it appears that PALB2 generally behaves as a low- to moderate-penetrance breast cancer susceptibility gene." (PMID 18053174, 2007). "In the first phase of the study, we sequenced PALB2 in its entirety in 50 French-Canadian breast cancer patients selected on the basis of age of diagnosis or family history." (PMID 18053174, 2007). "The strongest evidence favoring platinum-based/FOLFIRINOX strategies involves homologous recombination repair deficiency (HRD), especially alterations in germline breast cancer gene 1/2 (BRCA1/2) or partner and localizer of BRCA2 (PALB2), as well as broader genomic scar signatures." (PMID 42193022, 2026). "Breast cancer (BC) risk is significantly associated with pathogenic variants in at least eight susceptibility genes: BRCA1 (MIM#113705), BRCA2 (MIM#600185), PALB2 (MIM#610355), ATM (MIM#607585), CHEK2 (MIM# 604373), BARD1 (MIM#601593), RAD51C (MIM#602774), and RAD51D (MIM#602954)." (PMID 41230741, 2026).